APLN (apelin)
Diseases named in the same sentence as APLN in open-access papers (continued):
Sharing a sentence is not in itself a finding about the gene and the disease.
breast carcinoma (continued). "Furthermore, serum apelin levels were correlated with shorter survival, higher incidence of cancer recurrence and resistance to anticancer drugs in some human solid tumors, such as gastric cancer, lung adenocarcinoma, and breast cancer." (PMID 36902176, 2023). "In parallel with our studies, other groups have shown that inhibition of the apelin/APJ pathway improves efficacy of established anti-angiogenic treatments in glioblastoma, and prevents the metastasis associated with anti-angiogenic therapy in breast carcinomas." (PMID 32002127, 2020). "Here, we show that genetic and pharmacological inhibition of Apelin is a feasible strategy to reduce tumor blood vessel formation, vessel leakiness, and hypoxia, as well as to reduce suppressive immune cell infiltration, thereby significantly diminishing growth of primary lung and mammary tumors." (PMID 31267692, 2019). "To assess whether Apelin exerts its effects in the tumor epithelial cells or in the tumor endothelial cells, we used the E0771 mammary cancer model and specifically downregulated the expression of the Apelin receptor (Aplnr) in the cancer cells using shRNA (Fig EV2B)." (PMID 31267692, 2019). "Numerous studies have demonstrated that the Apelin/APJ axis is significantly overexpressed in various cancers, including lung adenocarcinoma, breast cancer, and HCC." (PMID 39434201, 2024). "Apelin muscle, ERK5, estrogen-dependent breast cancer, and hypoxia in the cardiovascular system signaling pathways were also affected." (PMID 35216124, 2022). "Apelin stimulates MCF-7 BC cell proliferation via the dose-dependent induction of cyclin D1 and amplified in breast cancer 1 (AIB1) and invasion potential by upregulating MMP1 expression, a mechanism also described in A549 lung adenocarcinoma cells." (PMID 33670492, 2021). "We, and others, found that the use of such competitive antagonistic peptides, like apelin-F13A or MM54, indeed led to reduced vascularization, attenuated tumor progression, and increased survival in GBM mouse models, as well as models of breast cancer." (PMID 32545380, 2020). "We confirmed that Apelin expression is enhanced in tumors of MMTV‐NeuT mice compared to epithelial cells isolated from the mammary gland of healthy mice (Fig EV1B), recapitulating human breast cancer and validating our model." (PMID 31267692, 2019). "Targeting Apelin not only reduces growth and angiogenesis in our lung and breast cancer models, but also, most importantly, it does not result in increased hypoxia within the tumor microenvironment." (PMID 31267692, 2019). "Intriguingly, we did not observe an increase in metastasis upon Apelin blockage alone in both of our mammary cancer models." (PMID 31267692, 2019). "Importantly, in mammary and lung cancer, Apelin prevents resistance to anti‐angiogenic receptor tyrosine kinase (RTK) inhibitor therapy, reducing growth and angiogenesis in lung and breast cancer models without increased hypoxia in the tumor microenvironment." (PMID 31267692, 2019).
Stroke (30 papers, 2015 to 2026). Sudden impairment of blood flow to a part of the brain due to occlusion or rupture of an artery to the brain. "In animal models of stroke and AD, apelin administration has been associated with improved cognitive outcomes and reduced brain damage [1434, 1435]." (PMID 40407975, 2025). "Another clinical study demonstrated that higher apelin levels were associated with increased risk of stroke (including ischemic and hemorrhagic stroke)." (PMID 36034795, 2022). "Our study sought to further investigate the relationship between apelin and atrial fibrillation and to determine apelin's predictive value for AF in patients with high risk of stroke." (PMID 34712712, 2021). "Aim of this study was to study the diagnostic value of apelin for AF in patients with high risk of stroke." (PMID 34712712, 2021). "In our previous research that included only patients with low risk of stroke, we showed that apelin is significantly decreased in patients with AF compared to patients without AF." (PMID 34712712, 2021). "Our previous research confirmed that apelin has high sensitivity and specificity to predict and quantify AF in patients with minimal cardiovascular comorbidities and low risk of stroke." (PMID 34712712, 2021). "In this study, lower apelin plasma levels are more associated with sECAS than with sICAS, and sICAS patients with severe stroke had lower levels of apelin." (PMID 31803136, 2019). "Low apelin-13 level in the patients was associated with death or major disability within 3-months, whereas patients with high apelin-13 levels showed a lower incidence of stroke and combined events after 1-year." (PMID 36034795, 2022). "Furthermore, the protective effect of apelin-13 on BBB post-stroke is significantly associated with the elevated expression of aquaporin-4 (AQP4), which is partly achieved by activating the extracellular signal-regulated kinase (ERK) and PI3K/Akt pathways." (PMID 36034795, 2022). "However, apelin as the target of an innovative pharmacological strategy to prevent stroke-associated myocardial atrophy needs further research." (PMID 34481466, 2021). "Currently, although mechanisms of the positive association between short LTL and stroke in the elderly remain elusive, multiple signaling pathways may contribute the positive association, e.g., apelin-apelin receptor mediated signaling pathway, histone deacetylases mediated epigenetic regulation." (PMID 31263449, 2019). "The development of a range of drugs targeting the apelin/APJ system holds promise for treating stroke." (PMID 39881878, 2024). "This study focuses solely on the antioxidative effects of the apelin/APJ system in stroke, overlooking other physiological roles such as anti-apoptosis and anti-neuroinflammation." (PMID 39881878, 2024). "In this review, we comprehensively discuss the physiological and pathological mechanisms of the apelin/APJ system in stroke." (PMID 39881878, 2024). "Currently, limited studies focus on the antioxidative effects of the apelin/APJ system in stroke, which remains largely unexplored." (PMID 39881878, 2024). "One study conducted in China on 244 AIS patients recruited within 24 h of stroke onset and 167 healthy controls showed that serum apelin-13 levels were lower in the patients compared to the healthy controls." (PMID 36034795, 2022). "Further large-scale multicenter clinical trials are needed, along with detailed subgroup analysis, to clarify the therapeutic value of apelin in stroke." (PMID 36034795, 2022). "A prospective study with 58 stroke patients confirmed that HUK promoted stroke recovery, enhanced cerebral reperfusion through up‐regulating vascular endothelial growth factor, apelin/APJ pathway, and the average perfusion time, was significantly shortened." (PMID 34808033, 2021). "The apelin/APJ system has been shown to exert effects against stroke, brain injury, and anxiety, thus producing a neuroprotective effect mostly from apelin-13 administration models." (PMID 32231577, 2020).
Stroke (continued). "More clinical research is wanted for an improved understanding of the apelin/APJ system in stroke and for the application of apelin in clinical practice for the patients with stroke." (PMID 32231577, 2020). "Apelin not only protects cells from death but also promotes angiogenesis against ischemic stroke and improves stroke recovery." (PMID 28167898, 2017). "A number of studies demonstrated that apelin-13 attenuated neuronal apoptosis in ischemic stroke, facilitating post-stroke recovery." (PMID 29085332, 2017). "Apelin-13 significantly increased the expression of angiogenic factor vascular endothelial growth factor and matrix metalloproteinase-9 14 days after stroke." (PMID 26391329, 2015). "In the present study, 30 min after intranasal delivery of apelin-13 resulted in significant high levels of apelin in the brain detected in the ipsilateral cortex of stroke animals." (PMID 26391329, 2015). "In a cerebral middle artery occlusion filament stroke model, apelin-36 reduced cell death and cerebral edema." (PMID 26391329, 2015). "This study demonstrates a noninvasive intranasal delivery of apelin-13 after stroke, suggesting that the reduced inflammatory activities, decreased cell death, and increased angiogenesis contribute to the therapeutic benefits of apelin-13." (PMID 26391329, 2015). "To elucidate the possible mechanisms of the proangiogenic effects of apelin, we measured the expression of angiogenesis related factors in the peri-infarct region at 14 days after stroke." (PMID 26391329, 2015). "Three days after stroke, mice received apelin-13 had significantly reduced infarct volume and less neuronal death in the penumbra." (PMID 26391329, 2015). "Angiogenesis illustrated by collagen IV + /5-bromo-2′-deoxyuridin + colabeled cells was significantly increased by the apelin-13 treatment 21 days after stroke." (PMID 26391329, 2015). "Apelin has also emerged as an important player in the regulation of brain function, including neuroprotection, cognitive processes, and cerebrovascular integrity, particularly in the context of stroke and ischemic injury [1422, 1429–1431]." (PMID 40407975, 2025). "Apelin-13, an endogenous peptide, improved neurological function after a stroke, reduced infarct volume, decreased cerebral edema, maintained the integrity of the BBB, inhibited neuronal apoptosis, and diminished neuroinflammation by lowering microglial activation in the MCAO model." (PMID 40724883, 2025). "HIF-1α and Sp1 induce the expression of apelin/APJ after a stroke." (PMID 39881878, 2024). "The evidence from experimental trials demonstrating the role and mechanism of apelin in stroke." (PMID 36034795, 2022). "Moreover, lower apelin was also related with a higher risk of death of patients with both ischemic stroke and HT, indicating that apelin is an independent protective factor in stroke patients." (PMID 36034795, 2022). "The evidence from clinical trials demonstrating the role of apelin in stroke." (PMID 36034795, 2022). "Our study demonstrated that in matched cohorts of patients with cardiovascular comorbidities and high risk of stroke, the cohort with AF had significantly lower concentration of apelin compared to the cohort without AF." (PMID 34712712, 2021). "Apelin ameliorated stroke and had neuroprotective effect by anti-apoptosis." (PMID 32231577, 2020). "Furthermore, post-stroke treatment with intranasal apelin-13 for three days can reduce infarct volume, reduce neuronal apoptosis, suppress inflammation, and increase angiogenesis." (PMID 31718027, 2019). "Similarly, intracerebral infusion of apelin-13 significantly decreases blood–brain barrier permeability and increases vascular endothelial growth factor levels in post-stroke mice." (PMID 31718027, 2019). "We found that post-stroke administration of apelin-36 significantly reduced infarct volume in rats." (PMID 29085332, 2017). "Amplified VEGF and apelin/APJ were observed in stroke rat brain." (PMID 26222055, 2015).
Stroke (continued). "Apelin-13 was given every day starting from 30 min after stroke." (PMID 26391329, 2015). "Apelin-13 was found to exert a neuroprotective action in a stroke model." (PMID 26273481, 2015). "Therefore, targeting the apelin/APJ system offers neuroprotection for stroke patients." (PMID 39881878, 2024). "Our observations suggest that apelin, despite its low specificity in the presence of several comorbidities indicating high risk of stroke, could still be used to rule out AF due to its high sensitivity." (PMID 34712712, 2021). "Furthermore, multiple molecules (e.g., apelin, HDAC4, RCAN1, α-synuclein), altered in stroke are implicated in aging process, premature disorders (e.g., Down syndrome, Werner syndrome) and age-related disorders (e.g., Alzheimer's disease, Parkinson's disease, Huntington's disease)." (PMID 31263449, 2019). "The present investigation evaluated the neuroprotective effect of intranasal delivery of apelin-13 and related mechanism against ischemic stroke in a mouse model of focal cerebral ischemia, explored long-term regenerative effects on angiogenesis and functional recovery after stroke." (PMID 26391329, 2015). "In this study, multiple signaling pathways involved in angiogenesis, such as AGE-RAGE, PI3K-Akt, apelin, HIF-1 and MAPK signaling, were found to be highly activated in the infarct core as well as in the peri-infarct region during stroke recovery." (PMID 39953545, 2025). "Growing evidence suggests that apelin and its receptor APJ play crucial roles in protecting neural cells post-stroke." (PMID 39881878, 2024). "This review aims to highlight the latest developments in the study of the apelin/APJ system’s functions and therapeutic potential in stroke patients." (PMID 39881878, 2024). "Further in-depth studies on the physiological and pathological effects of the apelin/APJ system and its potential mechanisms will greatly aid clinical prevention and intervention in strokes." (PMID 39881878, 2024). "The apelin/APJ system is extensively distributed in the brain and plays vital roles in regulating neurological diseases, including stroke." (PMID 39881878, 2024). "The apelin/APJ system plays a major role in the occurrence and development of several diseases, including strokes." (PMID 39881878, 2024). "Many potential anti-stroke candidates, such as OCT4B-190 and Apelin 13, produced neuroprotective effects against ischemic stroke via inhibiting GSK-3β." (PMID 36015166, 2022). "Xu’s group found that in ischemic experimental models and stroke patients, HUK promoted post-ischemic angiogenesis and cerebral perfusion via increasing vessel density, enhancing VEGF and apelin/APJ expression, and inducing ERK1/2 phosphorylation." (PMID 30050428, 2018). "One form of apelin, apelin-13, through kinase 5′AMP-activated kinase (AMPK) phosphorylation, lowers the process of mouse neuronal apoptosis after stroke." (PMID 29977292, 2018). "Chronic treatment of apelin-13 increased the angiogenesis and promoted the LCBF restoration and long-term functional recovery after stroke." (PMID 26391329, 2015). "To understand the mechanism of protective effect of apelin-13 at the cellular level, we performed the TUNEL staining to detect the apoptotic cell death at 3 days after stroke." (PMID 26391329, 2015). "Consistent with Western blot analysis, results from this assay verified that apelin-13-treated animals showed enhanced activity of MMP9, compared with those in stroke control animals 14 days after stroke." (PMID 26391329, 2015). "Due to the crucial roles of the apelin/APJ system in stroke, targeting it could provide novel treatments for stroke." (PMID 39881878, 2024). "This study extensively shows the apelin/APJ system and its antioxidative roles in stroke." (PMID 39881878, 2024). "Apelin and APJ expression levels vary at different time points during a stroke." (PMID 39881878, 2024).
Stroke (continued). "In addition, the apelinergic system, comprising apelin and APLNR, is important in recovery after stroke by inhibiting neuronal apoptosis and promoting angiogenesis through various molecular pathways." (PMID 37965346, 2023). "This article provides an overview of the latest advances in the understanding of the signaling pathways and physiological and pathophysiological role of apelin/APJ in pain, depression, anxiety, memory, epilepsy, neuroprotection, stroke, brain injury, and protection." (PMID 32231577, 2020). "In conclusion, the apelin/APJ system not only protects neurons from ischemic injury but also facilitates angiogenesis and prognosis of stroke, which may be mediated by the VEGF–VEGFR2 signaling pathway." (PMID 32194492, 2020). "Patients with severe stroke had lower levels of apelin (P = 0.005); the other three adipokines showed no such differences." (PMID 31803136, 2019). "Patients with severe stroke had lower levels of apelin (P = 0.005), while the other three adipokines showed no such difference." (PMID 31803136, 2019). "Apelin-13 was applied intracerebroventricular 15 min before reperfusion and resulted in a significantly ameliorated neurological deficit, infarct volume, brain edema and reduced TUNEL-positive cells 24 h after stroke." (PMID 30591020, 2018). "Therefore, the apelin-13-SIRT1–NF-κB pathway may represent an effective therapeutic strategy to reduce neuroinflammation and enhance stroke recovery." (PMID 40724883, 2025). "Moreover, apelin protected mouse neurons from cell death by reducing reactive oxygen species (ROS) production and activation of actin kinase, while changes in AMPK phosphorylation by apelin-13 blocked the process of mouse neuronal apoptosis after stroke." (PMID 35011661, 2021). "Moreover, the apelin/APJ system may work in coordination with VEGF to trigger vascular sprouting and CBF recovery from human urinary kallidinogenase (HUK)–treated stroke patients in an ERK1/2-dependent manner." (PMID 32194492, 2020).